BRAF (B-Raf proto-oncogene, serine/threonine kinase)
Diseases named in the same sentence as BRAF in open-access papers (continued):
Sharing a sentence is not in itself a finding about the gene and the disease.
tumor (continued). "Our series has demonstrated that the prognosis by PFS of patients with BRAF+ tumours, in whom BRAF mutations can be detected in cfDNA, is not significantly different from that of patients with BRAF+ tumours in whom BRAF mutations cannot be detected in cfDNA." (PMID 19861964, 2009). "Our series identified three cases in which cfDNA was positive for a BRAF mutation but the tumour DNA was negative." (PMID 19861964, 2009). "Often, tumour BRAF status is derived from a primary lesion that occurred months or years earlier." (PMID 19861964, 2009). "As these rare KRAS mutations and BRAF mutations are mutually exclusive with the others, it seems reasonable to test for their presence only in patients with KRAS codon 12 and 13 wild-type tumours." (PMID 19603018, 2009). "DNA sequence data for BRAF were obtained for 147 (84%) tumour samples." (PMID 19861964, 2009). "In three samples, BRAF mutations were identified in the serum but the tumour was BRAF mutation negative." (PMID 19861964, 2009). "In this regard, three samples in this study had BRAF mutations detected in the serum, wherein the tumour was BRAF mutation negative." (PMID 19861964, 2009). "Likewise, small-molecule inhibition of MEK abrogated tumour growth more profoundly in BRAF-mutant than KRAS-mutant tumour xenografts." (PMID 19603024, 2009). "If the outcome of patients with BRAF mutation is so poor, then the natural history of MSIhi tumours lacking BRAF mutation must be even more favourable; a recent study of patients with operable stage II or stage III CRC made the same suggestion." (PMID 19603024, 2009). "BRAF mutations are likely to precede MSI carcinomas since the frequency found in serrated polyps is similar to what is found in MSI CRC (P = 0.9112), but statistically different from what is found in microsatellite stable (MSS) tumours (P = 0.0191)." (PMID 18782444, 2008). "To determine whether constitutive BRAF* signaling is required for iBRAF* tumor maintenance, we performed doxycycline withdrawal study in iBRAF* transgenic animals with documented PCA by MRI or by physical examination." (PMID 19079609, 2008). "Tumours were screened for the presence of a RET/PTC rearrangement and for BRAF V600E mutation." (PMID 17712314, 2007). "The frequency of BRAF V600E mutation was similar, 38%, in our French and CTB tumours." (PMID 17712314, 2007). "Multivariate analysis revealed that MSI+ was the only significant independent predictor of BRAF mutation (RR = 6.3, 95%CI [1.2–32.3]; P = 0.028) in a model that included CIMP+, tumor site, histological grade, presence of infiltrating lymphocytes and mucinous appearance." (PMID 16403224, 2006). "Based on our and other studies which have shown absence of BRAF mutations in HTN one can assume that this tumor is not a variant of PTC." (PMID 16867191, 2006). "No oncogenic BRAF mutations were identified in exon 11 in any of the tumour biopsies evaluated, and only one oncogenic NRAS (61K) mutation was detected." (PMID 16880785, 2006). "Because the number of samples analyzed in the present study was limited, and the tumor cell content of some of the archival samples was scant, we were unable to determine the full diagnostic utility of LCPCR detection of the BRAF activating point mutation on indeterminate thyroid aspirates." (PMID 16606457, 2006). "In order to determine whether the characteristic clinicopathological features of tumors with BRAF mutation were due to their close association with MSI+ and CIMP+, we stratified tumours according to these phenotypes." (PMID 16403224, 2006). "Although the statistical power of this subgroup analysis was limited, the morphological features of infiltrating lymphocytes, poor histological grade and mucinous appearance were clearly associated with BRAF mutation regardless of tumor MSI status." (PMID 16403224, 2006). "They did not analyze the effect of BRAF mutations on the site of metastatic spread or other biological characteristics of the tumor." (PMID 15613230, 2004).
tumor (continued). "Nonetheless, these data suggest that some patients with pre‐existing T cell responses to tumor antigens in their TIL may benefit from a brief course of BRAF+/−MEKi therapy prior to initiation of ICB as was seen in the “Sandwich Therapy Arm” of the Secombit Trial." (PMID 41514118, 2026). "The genomic background of CRC, including alterations in KRAS, NRAS, PIK3CA, AKT1, BRAF, and the tumor’s MSI status, may modulate both the abundance and biological relevance of the immune regulators TIGIT and CD155, thereby affecting immune evasion and clinical outcome." (PMID 41596586, 2026). "This view is supported by Zeppernick (2015), who wrote that the BRAF mutation shows upregulation of glucose transporter-1 (GLUT1), which is an essential surface protein that leads to the increase in glucose metabolism required to overcome OIS-associated senescence and tumor progression." (PMID 40564801, 2025). "Importantly, this unbiased screening identified several hits that positively regulate PRMT5 expression, including oncoproteins such as HRAS and BRAF, whereas tumor suppressors like KEAP1 were identified as top-scoring hits that negatively regulate PMRT5 levels." (PMID 40091834, 2025). "Moreover, TLS may mitigate BRAF-driven tumor progression, highlighting its potential as a promising therapeutic target or biomarker in the context of precision oncology." (PMID 40959083, 2025). "In our patient, the tumor was negative for the common BRAF, KRAS, and NRAS mutations." (PMID 41169288, 2025). "The BRAF V600E mutation constitutively activates the MAPK/ERK pathway, an oncogenic signaling pathway that promotes the proliferation of SOX2+ embryonic cells, transforming them into tumor-initiating cells and stimulating processes such as angiogenesis and apoptosis inhibition." (PMID 40433410, 2025). "Tumor mutational burden (TMB; evaluated only in patients treated with tobemstomig and nivolumab plus ipilimumab based on favorable efficacy results) and the prevalence of BRAF V600E and V600K mutations were similar in patients in the tobemstomig arm and the nivolumab plus ipilimumab arm." (PMID 40993242, 2025). "In the two presented cases we determined preoperatively that surgical goal was diagnosis for BRAF V600E mutation and only debulking of tumor that could be readily resected without need for significant dissection off critical neurovascular structures." (PMID 39976897, 2025). "To investigate whether inhibition of ERK activation prevents TRIM63 phosphorylation and IRF-8 degradation, we found that treatment of BRAF-mutant tumor cells with Dabrafenib and Vemurafenib suppressed TRIM63 phosphorylation at S69 while concurrently increasing IRF-8 protein levels." (PMID 41315179, 2025). "Conversely, gene panels remain the predominant method for the detection of somatic driver mutations in tumor tissue, alongside WES in some institutions, given their high coverage of exonic regions where the majority of actionable alterations reside (e.g., EGFR, BRAF, PIK3CA, KRAS, BRCA1/2)." (PMID 41228293, 2025). "Therefore, any resistance mechanism that develops in the various components of the immune microenvironment in the context of BRAF/MAPK arising from the immune components within the tumor microenvironment can compromise the therapeutic benefit, necessitating further investigation." (PMID 40872623, 2025). "We selected KRAS, EGFR, BRAF, and MET mutations for inclusion in the multivariable model because they are among the most commonly altered driver mutations in LUAD and are known to significantly influence tumor behavior, prognosis, and response to targeted therapies." (PMID 40507306, 2025). "Therefore, secretory cells present in BRAF mutant CRCs may affect how this subtype of CRC interacts with the tumor immune microenvironment." (PMID 41039118, 2025).
tumor (continued). "Although BRAF mutation positivity provided a potential therapeutic pathway with BRAF inhibitors (like dabrafenib and vemurafenib) and MEK inhibitors (like trametinib) that block this specific pathway, slowing tumour growth, her frailty and rapid deterioration excluded systemic treatment." (PMID 41552174, 2025). "Clinically, while BRAF-mutated tumors have been associated with increased POMC transcription and ACTH secretion, there is currently limited data on their phenotype, including tumor size, invasiveness, or treatment response, due to the rarity of these mutations." (PMID 40364036, 2025). "Furthermore, the study highlights the high selectivity of these personalized drug combinations as a regimen effective for one BRAF V600E-mutant tumor may be less effective for another and vice versa." (PMID 40872623, 2025). "Second, absence of molecular biomarkers such as MSI and RAS/BRAF mutations represents a limitation, though our model incorporates tumor location and differentiation that may partially correlate with molecular subtypes." (PMID 41211422, 2025). "Additionally, mutations in oncogenes, such as KRAS, BRAF, and human epidermal growth factor receptor 2 (HER2), can drive aberrant cell proliferation and survival signaling, thereby contributing to tumor relapse." (PMID 39934876, 2025). "The results suggest that thyroid cells respond differently to BRAF activation and infer that follicular heterogeneity, a well-known feature of the thyroid gland both functionally and histologically, might influence tumor heterogeneity." (PMID 39956582, 2025). "Notably, the lack of survival difference based on tumor sidedness or BRAF mutation contrasts with patterns seen in older populations, suggesting distinct disease biology in younger patients." (PMID 40940860, 2025). "Here we provide proof of concept that non‐BRAF mutated SCC of the thyroid may develop from preexisting PTC, involving homozygous inactivation of several tumor suppressor genes, including KEAP1, which has previously been reported to be oncogenic in lung adenocarcinoma and lung SCC." (PMID 40600748, 2025). "Although some studies have explored CRT sensitivity in BRAF-mutant CRCs, their conclusions are inconsistent, with small sample sizes and lack of validation, highlighting the need for further investigation into the radiobiological characteristics of this kind of tumor." (PMID 40069844, 2025). "Her tumor was positive for a BRAF mutation, but she could not take BRAF/MEK inhibitors due to symptoms originating from BM, so she initially received two courses of nivolumab infusion." (PMID 40416034, 2025). "Moreover, RAS mutations may interact with other genetic changes, such as BRAF mutations in PTC, thereby affecting tumor behavior and treatment responses." (PMID 40507281, 2025). "However, current research on predicting BRAF V600E mutations in PTC patients with HT remains limited, partly because the inflammatory microenvironment in HT may alter the mutation’s role in tumor progression." (PMID 40900897, 2025). "Tumor site (proximal or distal, right-sided or left-sided) and stage (II or III) are independent prognostic indicators of CRC and may be confounders for our survival analysis of KRAS/BRAF mutations." (PMID 40279317, 2025). "Additionally, BRAF V600E drives the formation of an immunosuppressive tumor microenvironment." (PMID 40861443, 2025). "Interestingly, while the BRAF p.Val600Glu (V600E) mutation has been associated with reduced sensitivity to temozolomide in some contexts, our patient's BRAF-mutant tumor did not recur following standard chemoradiotherapy." (PMID 41473634, 2025). "We hypothesize that the effectiveness of these drugs may depend on the activated oncogene abundance when the tumor is driven by two distinct driver genes, detecting the abundance of EGFR mutations and BRAF mutations is crucial for optimizing the selection of TKIs in clinical practice." (PMID 40242250, 2025).
tumor (continued). "Regarding the potential practical application of the current findings in precision medicine, our data suggest that, based on the STR somatic mutation status of BRAF and APC in the BCC tumor tissue, it may be possible to select a group of patients who may respond well to some of the targeted therapy." (PMID 40427167, 2025). "In vitro melanoma models and transgenic BRAF/Pten mouse models demonstrated that Panx1 deletion increases T lymphocyte infiltration within the tumor microenvironment, although it does not significantly affect primary tumor formation, suggesting a dual role in tumor and immune regulation." (PMID 40978734, 2025). "Moreover, combination benefit is observed in in vitro native cell lines as well as in trametinib-resistant models and in vivo cell line and patient-derived tumor xenografts treated with the combination of clinical grade small molecule inhibitors of C/BRAF and MEK." (PMID 41023593, 2025). "Notably, Usp15 in the primary tumor cells is under BRAF/MAPK pathway control." (PMID 38750011, 2024). "However, it remains controversial whether BRAF V600E accurately reflects the malignancy and prognosis of the tumor." (PMID 38607456, 2024). "Also, patients were enrolled and treated from 2005 to 2010, when it was not routine to test for BRAF mutation status, PD-L1 expression, or tumor mutation burden." (PMID 38519525, 2024). "Furthermore, the GWMS was shown to be a predictor of clinical outcomes and that was independent of RAS/BRAF mutation status and primary tumor site." (PMID 38862615, 2024). "Whole exome sequencing results revealed that such EV-DNA carried tumor-specific genetic mutations, including those occurring on known oncogenes and tumor suppressor genes in neuroblastoma (ALK, CHD5, SHANK2, PHOX2B, TERT, FGFR1, and BRAF), and represented the entire exome." (PMID 39402599, 2024). "Additionally, BRAF expression was higher in patients with larger tumor sizes and higher grades." (PMID 38919805, 2024). "In addition, MEK inhibitors such as trametinib and cobimetinib target downstream elements of the MAPK pathway, offering a broader impact by affecting both tumor and normal cells, unlike BRAF inhibitors which only target mutated tumor cells." (PMID 39229331, 2024). "As a permanently activated kinase, mutated BRAF V600E can phosphorylate its downstream targets, such as MEK and ERK, and is associated with aggressive features, such as lymph node involvement, large tumor masses, or extrathyroid metastases, leading to a poor prognosis." (PMID 39407830, 2024). "Additionally, DN without BRAF V600E mutations were more frequently classified as neoplasms of uncertain behavior (ICD-10 D48.5) at the time of diagnosis (9 of 28; 34% vs. 5 of 51; 9.8%, P = 0.028; Fisher's exact test) than those with the mutation." (PMID 38371417, 2024). "Since the nucleic acid makeup of liquid biopsies reflects the total somatic genetic material from an individual, largely reflecting WT tissues, KR122 serves as a positive control for BRAF CRISPRdx in liquid biopsies and may give an indication of the tumor fraction in a sample." (PMID 39644903, 2024). "However, HER2 testing is not indicated if the tumor is already known to have a KRAS/NRAS or BRAF mutation." (PMID 39519088, 2024). "However, detailed information on the primary tumor site and BRAF genotype, which could be related to the distribution of GWMS, is needed to establish a rigorous comparison with previous reports." (PMID 38862615, 2024).
tumor (continued). "The use of type I BRAF inhibitors is limited to patients with tumors harboring a BRAF V600E mutation due to the risk of paradoxical activation of the MAPK pathway and accelerated tumor growth if used in patients with tumors harboring a RAF fusion, such as those involving BRAF or CRAF/RAF1." (PMID 38291372, 2024). "Moreover, the recent association of phenotypic and spatial characteristics of cancer-associated fibroblasts (CAFs) in the tumor microenvironment of NSCLC, with patient outcome, is worth exploring further in the context of RAF and MEK inhibitor targeted therapies in BRAF-mutant NSCLC." (PMID 38731852, 2024). "Combining BRAF inhibitors with immune checkpoint inhibitors may lead to better tumor suppression." (PMID 38244582, 2024). "BRAF mutation is a novel marker that lacks extensive validation, and it should therefore be used as a follow-up marker in cases with proven positive BRAF mutation status in tumor tissues rather than as a single biomarker." (PMID 39336882, 2024). "The BRAF status in the CRC5 sample was unknown since the mutational status of that patient’s tumor was not studied by the hospital." (PMID 39456686, 2024). "This study would be strengthened by availability of genetic analysis of tumours (such as microsatellite instability, KRAS and BRAF mutations), or specific details regarding adjuvant chemotherapy use, side-effect profile and completion which may be potential confounders." (PMID 38637820, 2024). "However, EREG and AREG overexpression have still been observed across patient tumors regardless of KRAS BRAF mutational status and primary tumor location." (PMID 40727266, 2024). "Detection of BRAF V600 mutations in different kinds of liquid biopsies from children with CNS tumors has been reported earlier, however, these reports describe either tumor-informed detection, or tumor-agnostic detection without subsequent targeted treatment." (PMID 38388693, 2024). "Correlation coefficients reveal a close relationship between biomarker values and tumor stage, suggesting the utility of these markers in monitoring the disease progression and risk stratification of patients, regardless of the presence of the BRAF mutation." (PMID 39767732, 2024). "Indeed, recent studies demonstrated that due to the intrinsic heterogeneity of intratumor, EGFR‐mutated NSCLC could seldom carry additional BRAF mutations, which is considered a predictor of resistance to EGFR inhibitors and tumor rapid progress." (PMID 38362771, 2024). "However, the strong association of BRAF expression with the hormone receptor–negative and non-luminal subtypes can be employed as a marker of more aggressive tumor biology." (PMID 38919805, 2024). "However, these interactions within the BRAF mutation class across multiple tumor types are not well understood." (PMID 38275886, 2024). "Notably, one patient with a BRAF V600E mutation in the primary tumor but not in the lymph nodes highlighted the heterogeneity of the BRAF genotype between the primary tumor, metastasis, and CTCs." (PMID 38398206, 2024). "No KRAS nor BRAF variants were detected in EGFR-positive tumor samples." (PMID 39063150, 2024). "Molecular analysis performed on tumor tissue did not detect the c.1799T>A, p.(V600E) variant in the BRAF gene, while IHC analysis of MMR proteins revealed an atypical profile characterized by the complete expression loss of all analyzed MMR proteins, indicative of a null IHC staining pattern." (PMID 38732303, 2024).